BOD1L1 (biorientation of chromosomes in cell division 1 like 1)
Description:
Component of the fork protection machinery required to protect stalled/damaged replication forks from uncontrolled DNA2-dependent resection. Acts by stabilizing RAD51 at stalled replication forks and protecting RAD51 nucleofilaments from the antirecombinogenic activities of FBH1 and BLM. Does not regulate spindle orientation.
Synonyms: BOD1L; FAM44A; KIAA1327; FLJ33215
Tractability: PROTAC: UniProt records ubiquitination sites on it; ubiquitination databases record sites on it; its protein half-life has been measured.
Gene: Protein-coding gene on chromosome 4 (13,568,738 to 13,627,725, reverse strand). Ensembl gene ENSG00000038219.
Subcellular location: Chromosome
Subcellular location (Human Protein Atlas): Nucleoplasm
Pathways (Reactome):
Gene expression (Transcription): Formation of WDR5-containing histone-modifying complexes
Gene Ontology:
Molecular function: protein binding
Biological process: DNA damage response; replication fork processing
Cellular component: Set1C/COMPASS complex; nucleoplasm; chromosome
Genetic constraint (gnomAD): Loss-of-function variants: 63 observed, 188.6 expected, observed/expected ratio (o/e) 0.33, 90% interval 0.27 to 0.41. The upper end of that interval is the gene's LOEUF score, 0.41, which puts it in group 1 of 6, group 1 being the genes least tolerant of losing a copy. Missense variants: 3,267 observed, 3,412.2 expected, observed/expected ratio (o/e) 0.96, 90% interval 0.93 to 0.99. Synonymous variants: 1,180 observed, 1,196.5 expected, observed/expected ratio (o/e) 0.99, 90% interval 0.94 to 1.03.
Homologues: Orthologues: chimpanzee BOD1L1 (99% identical), macaque BOD1L1 (96% identical), dog BOD1L1 (76% identical), rabbit BOD1L1 (76% identical), pig BOD1L1 (72% identical), rat Bod1l1 (69% identical), mouse Bod1l (68% identical), tropical clawed frog bod1l1 (30% identical), zebrafish bod1l1 (14% identical). Paralogues in human: BOD1 (3% identical), BOD1L2 (3% identical).
Diseases named in the same sentence as BOD1L1 in open-access papers:
BOD1L1 is named in the same sentence as 6 diseases in open-access papers, as found by Europe PMC text mining. Sharing a sentence is not in itself a finding about the gene and the disease. The quoted sentences say what the papers report.
glaucoma (2 papers, 2022 to 2023). Increased pressure in the eyeball due to obstruction of the outflow of aqueous humor. "In addition, a recent study using whole-exome sequencing identified rare variants and genes associated with IOP and glaucoma, including BOD1L1, ACAD10, and HLA-B, demonstrating the power of including and aggregating rare variants." (PMID 36980914, 2023). "BOD1L1, RALYL, LDB3, ACAD10, CDK11A, and DPF3 are also associated with glaucoma topical treatments (P < 1 × 10−5)." (PMID 36450729, 2022).
tumor (1 paper, 2021). "In contrast, significantly lower mRNA expression in tumor samples with high CIN70 score was observed for SMC1 (**), ERCC1 (***) and LIG4 (****), and a non-significant for XRCC4 (n.s.)and BOD1L1 (n.s.)." (PMID 33801877, 2021).
BOD1L1 also shares sentences with these, for which no sentence is quoted: Bladder Cancer (1 paper); Fanconi anemia (1); neurological disorders (1); Obesity (1).